TNF (tumor necrosis factor)
Diseases named in the same sentence as TNF in open-access papers (continued):
Sharing a sentence is not in itself a finding about the gene and the disease.
osteoarthritis (continued). "The clustering pattern in tissue from patient 7, where the healthy and diseased gingival tissue also clustered together, could be partly explained by the patient's history of osteoarthritis, which is a disease associated with elevated levels of circulating proinflammatory cytokines IL-6 and TNFα." (PMID 23029519, 2012). "This study comprehensively explored the molecular mechanisms of osteoarthritis via diverse bioinformatics approaches, emphasizing the TNF signaling pathway and its related genes." (PMID 40826778, 2025). "The expression of inflammatory biomarkers MyD88, p-IκBα, NF-κB, IL-6, IL-1β, and TNF-α in synovial fluid was lower in the curcumin-treated group compared to osteoarthritis rat groups." (PMID 40507179, 2025). "In patients undergoing osteoarthritis, synovitis develops, inducing effusion of inflamed SF rich in inflammatory factors such as IL-1, IL-6, IL-8, IL-17, and TNF-α." (PMID 40898269, 2025). "One study reported that liraglutide dose-dependently suppressed TNF-α-induced ROS in osteoarthritis." (PMID 41158135, 2025). "Vitamin D deficiency is associated with increased pain, poorer functional status, and elevated serum levels of TNF-α and IL-6 in individuals with osteoarthritis." (PMID 39940305, 2025). "In this context, vitexin, a flavone C-glycoside, demonstrated anti-inflammatory effects via the reduction of both TNF-α and IL-6 levels in rat chondrocytes and in chondrocytes from osteoarthritis patients." (PMID 40076701, 2025). "Studies have shown that P. lobata polysaccharides can reduce joint swelling symptoms, decrease the production of serum inflammatory cytokines TNF-α, IL-1β, and IL-6, and slow down inflammation in osteoarthritis (OA) in rats." (PMID 39795251, 2025). "TNF-α was used to stimulate HTB-94 chondrocytes to mimic the inflammation typical of degenerative joint disease progression." (PMID 41020853, 2025). "In this study, we also observed that in the osteoarthritis model, the levels of TNF-α, IL-1β, and IL-6 were significantly elevated." (PMID 39754163, 2025). "Immune infiltration analysis revealed distribution differences of immune cells in osteoarthritis samples, further emphasizing the TNF signaling pathway’s importance in inflammation regulation and providing new avenues for immunotherapy research." (PMID 40826778, 2025). "Previously, we documented that the phagosome formation and osteoarthritis pathway were influenced in chondrocytes from the Notch2tm1.1Ecan mice in the context of TNFα exposure." (PMID 40345585, 2025). "Three studies on patients with osteoarthritis compared active exercise to the control for TNF-α expression with follow-up periods ranging from 4 to 12 weeks." (PMID 40559680, 2025). "In RASFs, PKM2 expression is significantly elevated compared to osteoarthritis synovial fibroblasts, and its activity is modulated by inflammatory cytokines such as tumor necrosis factor-α (TNF-α) and interleukin-1β (IL-1β)." (PMID 41208991, 2025). "Mounting evidence highlights the link between osteoarthritis pathology and inflammatory markers, like interleukin (IL)-1β, tumor necrosis factor alpha (TNF-α), IL-6, and IL-17, 9]." (PMID 41446336, 2025). "It reduces the expression of inflammatory factors like IL-1β and TNF-α, showing potential therapeutic value for osteoarthritis, osteoporosis, and other orthopaedic conditions." (PMID 40431441, 2025). "Other studies also revealed that macrophages affect osteoclast differentiation via TNF-α, thereby promoting osteoporosis and defects in patients with Brucella osteoarthritis." (PMID 39967734, 2025). "While prior studies have confirmed the TNF signaling pathway’s role in osteoarthritis, our GSEA results suggest its suppression in osteoarthritis samples is closely tied to disease-associated immune regulatory mechanisms." (PMID 40826778, 2025). "BM-MSCs display anti-inflammatory effect by reducing IL-6, TNF-α and NF-κB, while there were increased levels of IL-10 in osteoarthritis patients." (PMID 40839685, 2025).
osteoarthritis (continued). "In the context of osteoarthritis (OA), inflammasome activation leads to the release of inflammatory mediators such as interleukin-1 (IL-1) and tumor necrosis factor-alpha (TNF-α)." (PMID 39857301, 2025). "Both TNFα and IL-1β are considered key inflammatory mediators in the pathogenesis of osteoarthritis." (PMID 40647239, 2025). "The roles of common inflammatory factors, including TNF-α, IL-1β, IL-6, and IL-10, in Brucella osteoarthritis have been referred to above and also have been described in detail elsewhere." (PMID 39967734, 2025). "Mei J, Sun J, Wu J, Zheng X. Liraglutide suppresses TNF-α-induced degradation of extracellular matrix in human chondrocytes: a therapeutic implication in osteoarthritis." (PMID 40372699, 2025). "In osteoarthritis (OA), these cells undergo pathological changes, shifting toward a catabolic phenotype that overproduces inflammatory cytokines (e.g., IL-1β, TNF-α) and matrix-degrading enzymes (e.g., MMPs, ADAMTS), accelerating cartilage breakdown." (PMID 41181141, 2025). "Because TNF-α signaling primarily via TNFR1 binds TRADD and RIPK1 to generate complexes that activate NF-κB, MAPKs, and caspases, IL-1β and TNF-α cooperate to enhance chronic inflammation in degenerative joint disease." (PMID 40506990, 2025). "Our findings indicate that Pioglitazone mitigates chondrocyte inflammation and osteoarthritis in murine models by inhibiting the expression of inflammatory mediators such as TNF‐α, IL‐6 and PGE2, and by preventing the degradation of aggrecan and collagen II." (PMID 40008494, 2025). "In conclusion, this study offers a systematic analysis of the role of TNF signaling pathway-related genes in osteoarthritis." (PMID 40826778, 2025). "In osteoarthritis, inflammatory biomolecules, for example, tumor necrosis factor-alpha (TNF-α) and interleukin 1β (IL-1β), get over-expressed and destroy the cartilage ECM through the promotion of MMPs, ADAMTS, and other catabolic enzymes." (PMID 40166527, 2025). "In a mouse model of traumatic osteoarthritis, both curcumin and curcumin-encapsulated nanoparticles inhibited the mRNA expression of pro-inflammatory factors such as IL-1β and TNF-α." (PMID 40431555, 2025). "In an initial experiment, we demonstrated that in the presence of TNFα, chondrogenic cells from Notch2tm1.1Ecan display enhanced phagosome formation and the osteoarthritis pathway." (PMID 40345585, 2025). "For example, the serum levels of inflammatory cytokines, including IL-6, IL-13, and TNF-α, were significantly elevated in patients with osteoarthritis secondary to meniscus injury." (PMID 39330256, 2024). "Recently, a randomized double-blind placebo-clinical trial by arthrocen showed that its oral administration diminished TNF-α and IL-17 while it increased anti-inflammatory IL-4 and IL-10 blood levels in patients with osteoarthritis." (PMID 38402151, 2024). "The inflammation in osteoarthritis is regulated by biochemical substances, such as prostanoids, cytokines (IL-1α, IL-1β, TNF-α, PGE2), proteases, and ROS produced by synoviocytes and chondrocytes." (PMID 39204123, 2024). "In synovial fluid and osteoarthritis (OA), IL-6 and TNF-α are the key immune mediators and inflammatory markers." (PMID 39458926, 2024). "Due to inflammation, NO production increased through the NF-κB signaling pathway, which regulates three pro-inflammatory cytokines of osteoarthritis, including IL-1β, IL-6 and TNF-α." (PMID 39204123, 2024). "Three main pro-inflammatory cytokines that engage in the pathophysiology of osteoarthritis are IL-1β, IL-6, and TNF-α." (PMID 39204123, 2024). "Patients with osteoarthritis exhibit higher levels of inflammatory cytokines IL-1β, IL-6, and TNF-α in the blood, synovial fluid, and cartilage tissue compared to healthy individuals." (PMID 38542192, 2024). "Verbascoside at 20 mg/kg doses prevented the development of osteoarthritis in rats by lowering proinflammatory interleukin (IL-1β, IL-6) and tumor necrosis factor (TNF)-α." (PMID 38790677, 2024).
osteoarthritis (continued). "Previous studies indicate that interleukin-1 beta (IL-1β) and tumour necrosis factor alpha (TNFα) are instrumental in the progression of osteoarthritis." (PMID 38200556, 2024). "IL-1β and TNF-α have been shown to incite the progression of osteoarthritis by promoting the catabolic cascade." (PMID 38255841, 2024). "IL-1β, IL6, and TNF-α induce chondrolysis, leading to arthralgia and/or the progression of osteoarthritis." (PMID 39850191, 2024). "This is in line with other studies, which show a decline in the levels of IL-1β and TNFα in the late stages of osteoarthritis compared to earlier stages of the disease." (PMID 38200556, 2024). "The pathogenesis of osteoarthritis involves the activation of the inflammatory cascade through the stimulation of various cytokines such as TNF-α, IL-10, IL-8, and IL-1β." (PMID 38327525, 2024). "THP-1 cells underwent treatment with β-amyrin, stigmasterol, and the YTPS formulary extract, and individual herbal extracts were evaluated with pivotal cytokines contributing to the progression of osteoarthritis, IL-1β, IL-6, and TNF-α." (PMID 39204123, 2024). "Visfatin, a pro-inflammatory adipokine, plays a role in osteoarthritis pathogenesis by upregulating inflammatory mediators such as TNF-α, IL-6, IL-1β, and various MMPs and ADAMTS enzymes, which are principal agents in cartilage catabolism." (PMID 38800150, 2024). "Here, we investigated Cx43 modulation mediated by inflammatory stimuli involved in osteoarthritis, i.e., 10 ng/mL Tumor Necrosis Factor alpha (TNFα) and/or 1 ng/mL Interleukin-1 beta (IL-1β), in primary chondrocytes (CH) and osteoblasts (OB)." (PMID 39126115, 2024). "In the group of our chronic patients prevail osteoarthritis and meniscal tears, which can result in higher levels of TNF- α and IL-6." (PMID 39519568, 2024). "IL-1β and TNF-α expedite the advancement of osteoarthritis through the facilitation of the catabolic cascade." (PMID 38255841, 2024). "Several studies have demonstrated the crucial involvement of TNF-α in the pathogenesis of cartilage degradation and osteoarthritis." (PMID 37505889, 2023). "Inflammation, which is mainly sustained by pro-inflammatory cytokines such as IL-1b, TNF, and IL-6, plays an important role in osteoarthritis progression." (PMID 37316888, 2023). "Inflammation is an important factor in disease progression of osteoarthritis, which is mediated by the proinflammatory cytokines such as TNFα." (PMID 37564645, 2023). "to inhibit the TNF-α/COX2 pathway in the treatment of osteoarthritis and study its effect as an antimicrobial, antibiofilm, and antioxidant." (PMID 36757520, 2023). "The release of inflammatory cytokines such as tumor necrosis factor α (TNFα) is an important trigger of early osteoarthritis and is a proposed biomarker candidate to monitor osteoarthritic progression." (PMID 36385655, 2023). "According to a recent study, CASZ1 plays an anti-inflammatory role in osteoarthritis by downregulating interleukin 6 (IL-6) and tumor necrosis factor-alpha (TNF-α), while preventing apoptosis of chondrocytes, which are unable to regenerate." (PMID 37509718, 2023). "In patients with osteoarthritis, these cytokines could also result in the impairment of tissues in the musculoskeletal system, wherein IL-1b could play a critical role in cartilage damage and TNF-alpha was associated with triggering further inflammatory reactions." (PMID 38173729, 2023). "In rat cartilage tissue of osteoarthritis, miR-137 is also downregulated, and its over-expression can reduce the inflammatory factors (TNF-α, IL-1β, IL-6) via downregulating the TCF4-AMPK/NF-κB pathway." (PMID 38138985, 2023). "Altogether, these results indicate that plugs of cartilage cultured with 1 ng/mL TNFα and 0.1 ng/mL IL-1β develop a “OA-like” phenotype and constitute a good and representative osteoarthritis in vitro model for this pathology." (PMID 36271312, 2023).
osteoarthritis (continued). "In osteoarthritis, NF-κB is frequently activated, often in response to factors like cytokines, including IL-1β and TNF-α, which stimulate the release of MMPs and other catabolic enzymes, thereby exacerbating osteoarthritis." (PMID 38132929, 2023). "High levels of representative pro-inflammatory cytokines, IL-1β and TNF-α, have been observed in the synovium of patients with osteoarthritis." (PMID 37175932, 2023). "Cartilage plugs exposed to this cocktail of TNFα and IL-1β were therefore considered as a simplified in vitro model of osteoarthritis." (PMID 36271312, 2023). "Osteoarthritis is known to be promoted by inflammatory cytokines (TNF-α, IL-1, IL-6, IL-17, etc.)that stimulate the secretion of matrix metalloproteinases (MMPs) from synovial fibroblasts." (PMID 37623223, 2023). "Synovial tissue IL-18 mRNA levels were significantly higher in AOSD patients than in osteoarthritis patients, whereas TNF-α and IL-8 mRNA levels were higher in RA patients than in AOSD patients." (PMID 37415987, 2023). "After defining the articular part of the in vitro osteoarthritis model, a cocktail of human recombinant TNFα and IL-1β at low concentration was administered to cells as these 2 pro-inflammatory cytokines are present in joints suffering from OA." (PMID 36271312, 2023). "Donepezil was reported to exert a chondroprotective effect in osteoarthritis in vitro by suppressing TNF-α-induced expression of matrix metalloproteinase-13." (PMID 37240337, 2023). "IL6, TNFα, and MMP13, all of which are associated with osteoarthritis (OA) and compromised joint health, have been observed in MT-COMP joints." (PMID 37892235, 2023). "Validation through real-time PCR and Western blotting of synovial tissue corroborated elevated expression of NOD2 and TNF-α in osteoarthritis patients." (PMID 38124066, 2023). "For instance, 10 mg/kg per day of shikonin was found to suppress inflammation by modulating PI3K/Akt signaling pathway in a rat model of osteoarthritis by inhibiting TNF-α, IL-1β, and inducible nitric oxide synthase (iNOS) levels." (PMID 37763983, 2023). "Despite the fact that predominant pro-inflammatory cytokines such as IL-1β, TNF-α, IL-15, or IL-6 are well described in human medicine research, it is not documented which biomarker is the gold standard for evaluating osteoarthritis in animal species." (PMID 37443993, 2023). "In the chondrocytes in osteoarthritis, exosomes have been shown to reduce inflammatory mediators such as tumor necrosis factor-α (TNF-α), IL-6, prostaglandin E2 (PGE2), and NO." (PMID 36678850, 2023). "Among them, interleukin 1 beta (IL-1β) and tumor necrosis factor-alpha (TNF-α) are the main factors that accelerate degenerative arthritis by inducing the expression of other cartilage ECM-degrading factors (iNOS, PGE2, MMPs, and ADAMTS-4)." (PMID 35326137, 2022). "TNF-α, and IL-6, both pro-inflammatory cytokines, contribute to cartilage degradation in osteoarthritis and facilitate pain initiation and persistence." (PMID 35941593, 2022). "It was found that miR-199a-5p also inhibits visfatin (a pro-inflammatory adipokine)-induced IL-6 and TNF-α production to mitigate the progression of osteoarthritis." (PMID 36561044, 2022). "Local synovial proinflammatory cytokines IL-1β, TNF-α, and IL-6A are detectable in early osteoarthritis and are related to the disease progression and joint pain of OA." (PMID 35656456, 2022). "In a recent study, microfracture failure was found to have a positive correlation with TNF-α revealed by correlation analyses between the osteoarthritis research society international (OARSI) total score and the cytokines measurement." (PMID 36568290, 2022). "The levels of serum myostatin and interleukin (IL)-1β were significantly elevated in synovial fluid from RA patients than that from osteoarthritis patients, immunohistochemistry data also revealed a positive correlation between myostatin and IL-1β, TNF-α." (PMID 36330524, 2022).
osteoarthritis (continued). "Seahorse hydrolysate decreased some proinflammatory factors related to osteoarthritis development, such as reduction of tumor necrosis factor-alpha and leptin as well as oxidative stress." (PMID 35509713, 2022). "Osteoarthritis-induced rats increased in TNF-α, COX-2, and NO levels, with levels of the OA group significantly higher than those of the control group (p < 0.05)." (PMID 35866033, 2022). "The presented results indicate that the same levels of pro-inflammatory cytokines (IFN-γ, TNF-α, IL-12 (p70)) before and after the 21-day general rehabilitation reflect a dynamic inflammatory status of osteoarthritis patients after hip or knee implantation." (PMID 35625533, 2022). "A review of mechanical loading on osteoarthritis showed that mechanical load activated multiple inflammatory pathways, such as IL-1β, TNF-α, inducing chondrocyte apoptosis, synovial inflammation and subchondral bone dysfunction, finally leading to OA." (PMID 36246900, 2022). "The downregulation of serum TNF-α has been correlated with improvements in the VAS scores of patients with osteoarthritis after treatment." (PMID 35061744, 2022). "In Module 2, the PI3k-Akt signaling pathway is closely involved in the inflammatory response to induce MMPs, Adamts, IL-1β, and TNF-α in osteoarthritis." (PMID 35563641, 2022). "We observed a marked increase in 11β-HSD1 activity in bone in RA relative to osteoarthritis bone, whilst the pro-inflammatory cytokine TNFα upregulated 11β-HSD1 within osteoblasts and osteoclasts." (PMID 35806338, 2022). "In adjuvant-induced arthritis and models of air sac edema in rats, treatment with 10 ml/kg of CM for three weeks, reduced serum TNF-α, claw edema and the osteoarthritis index." (PMID 35493477, 2022). "ELISA results demonstrated that exogenous α2MRS significantly inhibited the induction of MMP-13 (p = 0.001), TNF-α (p = 0.005), and IL-6 (p < 0.001) activity in IL-1β-induced human primary osteoarthritis chondrocytes." (PMID 36133821, 2022). "FLS isolated from RA (n = 14) and osteoarthritis (OA, n = 4) patients were stimulated with recombinant interleukin-17 (IL-17; 5 ng/mL) and tumor necrosis factor alpha (TNF-α; 5 ng/mL) for 24 h." (PMID 35216458, 2022). "A large number of inflammatory mediators including IL-6, TNF-α and IL-1β were detected in osteoarthritis." (PMID 35563622, 2022). "Numerous proinflammatory cytokines, including tumor necrosis factor-α, contribute to the maintenance of the catabolic phenotype during the progression of osteoarthritis." (PMID 35866033, 2022). "Molecules involved in cartilage degeneration, or being markers of inflammation in osteoarthritis, are cytokines, such as tumor necrosis factor α (TNFα), interleukins (IL), type II collagen, aggrecan, and metalloproteinases." (PMID 35406644, 2022). "In the case of RA and compared to both healthy controls and patients with osteoarthritis, IL-32 expression was higher in RA patients; moreover, the synovial biopsies of RA patients exhibit a reduction of IL-32 upon anti-TNFα treatment." (PMID 35281066, 2022). "In osteoarthritis, many other cytokines (e.g., IL-6, TNF-α, IL-15) also play an important role during the progression of the disease." (PMID 35885038, 2022). "TNF-α, together with IL-1β, IL-6, and IL-17 are also known to upregulate angiogenic substances, as seen in pathogenesis of osteoarthritis." (PMID 34172047, 2021). "Other NSAIDs (i.e., diclofenac sodium, indomethacin, and nabumethon) raised the TNF-α serum level in osteoarthritis patients." (PMID 34201817, 2021). "In particular, IL-1β and TNF-α can stimulate IL-6 expression, and IL-6 is a biomarker reflecting the severity of osteoarthritis." (PMID 34574569, 2021). "The content of TNF-α, EGF and sAPO-1/Fas in Helicobacter pylori-positive gastroduodenopathies caused by NSAIDs in patients with osteoarthritis in the dynamics of treatment 1 month (M ± m)." (PMID 34104240, 2021).